LGALS1 (galectin 1)
Diseases named in the same sentence as LGALS1 in open-access papers (continued):
Sharing a sentence is not in itself a finding about the gene and the disease.
Parkinson disease (4 papers, 2019 to 2023). A progressive degenerative disorder of the central nervous system characterized by loss of dopamine producing neurons in the substantia nigra and the presence of Lewy bodies in the substantia nigra and locus coeruleus. "The serum concentrations of galectin-3 and -4 are increased, but galectin-1 in the cerebrospinal fluids is decreased in patients with Parkinson's disease." (PMID 34720894, 2021). "Galectin-1 plays an anti-inflammatory function and suppresses neuronal degeneration in the 1-methyl-4-phenyl-1,2,3,6-tetrahydropyridine-induced Parkinson's disease model." (PMID 34720894, 2021).
periodontal disease (4 papers, 2021 to 2024). "Both Galectin-1 and Galectin-3 seem to have outstanding diagnostic accuracy for the identification of periodontal disease, an acceptable ability to measure periodontal disease activity and the severity of inflammatory status." (PMID 38743248, 2024). "The important role of galectin-1 has been repeatedly discussed in context of periodontal diseases; thereby, it was reported to be mainly involved in lipopolysaccharide-related reaction of periodontal ligament cells." (PMID 34925639, 2021).
retinal disease (4 papers, 2015 to 2024). "Galectin-1, a beta-galactoside-binding protein that plays an important role in cell adhesion and proliferation, has been previously implicated in retinal disease." (PMID 30176221, 2018). "Our current data provided a novel insight into anti-VEGF-A therapeutic strategies in terms that aflibercept traps galectin-1, a VEGF-A-independent VEGFR2 ligand associated with the pathogenesis of PDR as well as various retinal disease models." (PMID 26648523, 2015). "Moreover, the present in vitro findings contrasted these two VEGFR2 ligands in terms of the preferential gene upregulation of LGALS1 by IL-1β and VEGF165 by hypoxia in Müller glial cells, which are activated in various retinal diseases." (PMID 29170525, 2017).
squamous cervical cancer (4 papers, 2015 to 2021). "Further studies are also warranted to elucidate whether LGALS1 could regulate cisplatin chemosensitivity of squamous cervical cancer cells and the underlying mechanisms." (PMID 32047564, 2020). "In our previous study, we have identified 16 proteins, including galectin-1, which were down-regulated in squamous cervical cancer tissue after NACT relative to the level before chemotherapy by using Proteomic Profiling." (PMID 28842515, 2017). "Initially, the effect of chemotherapy on the expression of galectin-1 and integrin α5β1 in squamous cervical cancer samples was evaluated." (PMID 28842515, 2017). "The expression of galectin-1 and integrin α5β1 in 35 matched primary squamous cervical cancer biopsies before and after cisplatin-based NACT were evaluated using immunohistochemistry." (PMID 28842515, 2017). "Galectin-1 and integrin α5β1 proteins were detected both in the tumor cells and in the stroma cells of squamous cervical cancer samples." (PMID 28842515, 2017). "In squamous cervical cancer patients who received radiation therapy, a recent study reported that expression of galectin-1 by the tumor was an independent predictor for local recurrence and poor survival." (PMID 26066796, 2015). "The present study investigated the correlations between expression of galectin-1, -3 and -9 and survival in a squamous cervical cancer cohort (n = 160) following the REMARK recommendations for prognostic tumor marker studies." (PMID 26066796, 2015). "The present study, performed in a consecutive cohort of squamous cervical cancer patients, shows that tumor galectin-1 is a marker for poor survival." (PMID 26066796, 2015). "High levels of galectin-1 and integrin α5β1 in stromal were associated with a negative chemotherapy response in squamous cervical cancer patients treated with cisplatin-based NACT." (PMID 28842515, 2017). "Collectively, chemotherapy down-regulated the expression of galectin-1 and integrin α5β1 both in tumor cells and stromal cells of squamous cervical cancer, suggesting galectin-1 and integrin α5β1 protein were involved in cervical tumor response to chemotherapy." (PMID 28842515, 2017). "However, whether galectin-1 expression correlates with chemoresistance in squamous cervical cancer patients is currently unknown." (PMID 28842515, 2017). "In the current study, we reported that galectin-1 and integrin α5β1 expression in tumor cells and stromal cells were significantly down-regulated after NACT in patients with squamous cervical cancer." (PMID 28842515, 2017). "In conclusion, our current study demonstrated that the expression of galectin-1 and integrin α5β1 in stromal can predict the responses to NACT in squamous cervical cancer." (PMID 28842515, 2017). "Galectin-1 and integrin α5β1 expression in stromal may serve as a prediction of the responses to cisplatin-based NACT for patients with bulky squamous cervical cancer." (PMID 28842515, 2017). "Thus, we suggested that the expression of galectin-1 and integrin α5β1 protein in stromal cells but not in tumor cells was associated with responses to NACT among squamous cervical cancer patients." (PMID 28842515, 2017). "Although galectin-1 and integrin α5β1 confer chemoresistance to certain types of cancer, whether their expression predicts the response to cisplatin-based neoadjuvant chemotherapy (NACT) in squamous cervical cancer remains unclear." (PMID 28842515, 2017).
triple-negative breast carcinoma (4 papers, 2016 to 2025). An invasive breast carcinoma which is negative for expression of estrogen receptor (ER), progesterone receptor (PR), and human epidermal growth factor receptor 2 (HER2). "In our study, the expression levels of Vimentin, Snail, and Slug, which act primarily on the EMT pathway, were decreased by the miR-22-3p overexpression and galectin-1 suppression by siRNA in triple-negative breast cancer cells." (PMID 39996781, 2025). "Herein, we report that galectin-1 knockdown can inhibit cancer progression in both hormone-positive and triple-negative breast cancer cells." (PMID 39996781, 2025). "Our results imply that extracellular galectin-1 has potential as a therapeutic target for triple-negative breast cancer." (PMID 28415760, 2017). "In hormone receptor-positive breast cancer cells, galectin-1 knockdown mainly inhibited cell cycle-related substances and induced G0/G1 arrest, whereas in triple-negative breast cancer cells, it suppressed molecules related to the epithelial–mesenchymal transition pathway." (PMID 39996781, 2025). "Interestingly, in the MDA-MB-231 cells, a triple-negative breast cancer cell line, the expression of galectin-1- and EMT-related markers Vimentin and Slug were significantly reduced by miR-22-3p overexpression (p < 0.05 and p < 0.05, respectively)." (PMID 39996781, 2025). "Therefore, the regulation of the galectin-1/miR-22-3p axis is expected to be an important therapeutic target via EMT regulation in triple-negative breast cancer treatment." (PMID 39996781, 2025). "To elucidate the molecular mechanisms underlying galectin-1-mediated cancer progression, we established galectin-1 knock-down cells via retroviral delivery of short hairpin RNA (shRNA) against galectin-1 in two triple-negative breast cancer (TNBC) cell lines, MDA-MB-231 and Hs578T." (PMID 28415760, 2017). "The most remarkable finding from this study is that the miR-22-3p/galectin-1 axis affects cancer progression by regulating the cell cycle in hormone receptor-positive breast cancers and by affecting EMT mechanisms in triple-negative breast cancers." (PMID 39996781, 2025). "We observed higher levels of galectin-1 in the two triple-negative breast cancer (TNBC) cell lines, MDA-MB-231 and Hs578T, than in non-TNBC cell lines." (PMID 28415760, 2017).
acute myeloid leukemia (3 papers, 2015 to 2024). Acute myeloid leukemia (AML) is a group of neoplasms arising from precursor cells committed to the myeloid cell-line differentiation. "We therefore interrogated The Cancer Genome Atlas (TCGA) to test whether expression of galectin-1 correlated with overall survival in 132 patients with acute myeloid leukemia." (PMID 39383242, 2024). "Interestingly, CCAAT/enhancer binding protein α(C/EBPα) physically interacts with HIF-1α and directly binds to the −48 to −42 bp region to activate the expression of galectin-1 and control the differentiation of human acute myeloid leukemia cells." (PMID 26413750, 2015).
age-related macular degeneration (3 papers, 2020 to 2023). Age-related loss of vision in the central portion of the retina (macula), secondary to retinal degeneration. "In line with this, in a mouse model of age-related macular degeneration, increased levels of galectin-1 enhanced the EMT of RPE cells and subretinal fibrosis via activation of the TGF-β pathway, whereas its knockdown blocked both effects." (PMID 37628816, 2023). "Moreover, in an experimental mouse model for age-related macular degeneration, the expression of galectin-1 was increased, while its lack substantially reduced the formation of choroidal neovascularization, a vision-threatening progression of the disease in humans." (PMID 37628816, 2023). "First, in a mouse model of age-related macular degeneration (AMD), galectin-1 was involved in neovascularization and subretinal fibrosis, which is the end-stage of AMD." (PMID 34356834, 2021).
anaplastic large cell lymphoma (3 papers, 2014 to 2022). Anaplastic large cell lymphoma (ALCL) is a rare and aggressive peripheral T-cell non-Hodgkin lymphoma, belonging to the group of CD30-positive lymphoproliferative disorders, which affects lymph nodes and extranodal sites. "Galectin-1 is expressed in anaplastic large cell lymphoma (ALCL) as well as Hodgkin lymphoma (HL)." (PMID 24589677, 2014). "Anaplastic large cell lymphoma (ALCL) overexpresses galectin-1, and the expression level is strongly correlated with c-Jun in the AP-1 transcription complex." (PMID 35677161, 2022). "We demonstrated that cell surface glycosylation appeared to regulate cell adhesive or invasive properties to galectin-1 in human anaplastic large cell lymphoma (H-ALCL) cell line." (PMID 25573487, 2015). "To elucidate the biological roles of galectin-1 in cell adhesion and invasion of human anaplastic large cell lymphoma, we performed cell adhesion and invasion assays using the anaplastic large cell lymphoma cell line H-ALCL, which was previously established in our laboratory." (PMID 24589677, 2014).
astrocytic tumor (3 papers, 2009 to 2018). A glial tumor of the brain or spinal cord showing astrocytic differentiation. "In contrast, in astrocytic tumors, galectin-1 increases cell migration, and has recently been reported to increase adhesion, proliferation and migration, in combination with vascular endothelial growth factor, in human umbilical vein endothelial cells, as a result of neuropilin-1 binding." (PMID 19898636, 2009).
bladder transitional cell carcinoma (3 papers, 2010 to 2020). The most common morphologic subtype of urinary bladder carcinoma (over 90% of cases). "The 18F-labeled galactodendritic unit 4 has high binding to UMUC3 bladder transitional cell carcinoma cells containing a high expression of galectin-1, and therefore, UMUC3 cells were used to develop an orthotopic BCa model." (PMID 32005776, 2020). "The expression of galectin-1 and galectin-3 was investigated in 38 human bladder transitional cell carcinomas of different histological grade and clinical stage and in five normal urothelium samples." (PMID 23658855, 2010).
depression (3 papers, 2011 to 2021). "Galectin-1 and -3 knockout mice exhibit impaired stress-coping and increased compulsive-like behavior, implying that galectin-1 and -3 are related to depression and obsessive-compulsive-like behaviors." (PMID 34720894, 2021). "The other YWHAZ abnormalities were the interactions with RNPS1 and LGALS1 in schizophrenia; the interactions with MYCBP2, PRDX1 or TP1l in bipolar disorder; the interactions with RPLP2 and VIM in major depression; and the interactions with RPLP0 in both schizophrenia and major depression." (PMID 22373040, 2011).
gastric tumors (3 papers, 2025 to 2026). "Clinically, galectin-1 was highly expressed in gastric tumors, correlated with advanced stage, and predicted poor prognosis." (PMID 42157933, 2026). "In gastric tumors, cancer-associated fibroblasts—not the malignant epithelium—are the principal source of Galectin-1, establishing a stromal signaling loop that promotes invasion and suppresses antitumor immunity." (PMID 40710343, 2025).
invasive carcinoma (3 papers, 2005 to 2019). A carcinoma that is not confined to the epithelium, and has spread to the surrounding stroma. "High levels of galectin-1 expression in stromal cells were observed in the invasive carcinoma compared to the non-invasive carcinoma (p = 0.004), and the levels of galectin-1 expression in CAS cells showed positive correlation with FIGO stages of EOC." (PMID 26589590, 2015). "Some of the most significant differential mRNA expressions were found for COL1A1, SPARC, and LGALS1 that were stronger expressed in invasive carcinoma compared to high‐grade dysplasia, and the opposite was shown for S100A7, which was stronger expressed in high‐grade dysplasia." (PMID 31454186, 2019). "The average expression levels of two genes (Cdc42 and Galectin-1) and four genes (p21, Erk1, Mucin 3, and Laminin β-3) were significantly lower and higher, respectively, in the flat-type adenoma group than those in the early invasive carcinoma group." (PMID 15785755, 2005).
ischemia (3 papers, 2017 to 2026). A hypoperfusion of the BLOOD through an organ or tissue caused by a PATHOLOGIC CONSTRICTION or obstruction of its BLOOD VESSELS, or an absence of BLOOD CIRCULATION. "In a rat model of ischemia, galectin-1 increases brain-derived neurotrophic factor (BDNF) expression in astrocytes." (PMID 36008956, 2022). "It is reasonable to speculate that the more advanced stages of CRVO and BRVO would exhibit higher levels of ischemia-induced galectin-1, which is also thought to contribute to the soaring rise in galectin-1 along with the severity of DR on top of AGE-triggered galectin-1." (PMID 29170525, 2017).
ischemic stroke (3 papers, 2020 to 2024). A stroke disorder caused by obstruction of blood flow to the brain, due to thrombotic (local blood clot formation) or embolic (due to a blood clot or other material traveling from another site) event. "The transfer of galectin-1-overexpressing stem cells into the mice strongly reduced infarct volume upon ischemic stroke." (PMID 36873388, 2023). "However, the association between the galectin-1 level and incident ischemic stroke was not significant." (PMID 33244142, 2020).
juvenile idiopathic arthritis (3 papers, 2013 to 2018). Juvenile idiopathic arthritis (JIA) is the term used to describe a group of inflammatory articular disorders of unknown cause that begin before the age of 16 and last over 6 weeks. "Galectin-1 expression is downregulated and galectin-3 expression is upregulated in synovial tissue from patients with juvenile idiopathic arthritis." (PMID 30525048, 2018). "In human patients, in situ immunohistochemistry showed remarkably reduced expression of galectin-1 in synovial tissue from patients with long duration of juvenile idiopathic arthritis (JIA)." (PMID 24416634, 2013).
Lewis lung carcinoma (3 papers, 2013 to 2024). "Lewis lung carcinoma cells in mice show metastasis to the lung when the cells express Galectin-1 (Gal-1), a large carbohydrate-binding protein encoded by LGALS1, suggesting novel targeting strategies for Gal-1 in cancer." (PMID 23671674, 2013). "Previously, radiation treatment of Lewis lung carcinoma in mice has demonstrated an increase in galectin-1 secretion." (PMID 38539500, 2024).
liver diseases (3 papers, 2017 to 2021). "According to the current systematic analyses, the role of galectin-1,-3,-4, and -9 was studied in patients with liver diseases." (PMID 34778306, 2021). "Of these disease-associated proteins and proteins related to Galectin-3, NDRG1 showed a close relationship to carcinoma and liver diseases, and CD166, S100A11 and Galectin-1 were also related to carcinoma." (PMID 28701735, 2017).
Nasal polyposis (3 papers, 2010 to 2024). Polypoidal masses arising mainly from the mucous membranes of the nose and paranasal sinuses. "In patients with nasal polyps, glucocorticoid treatment has been shown to enhance galectin-1 expression in their surgical resection." (PMID 39290694, 2024). "We therefore decided to investigate the expression of genes that code these two anti-inflammatory proteins (annexin-1 and galectin-1) in nasal polyps and their response when systemic glucocorticoids are given." (PMID 20549082, 2010). "We concluded that there is an increased expression of genes that code the anti-inflammatory proteins annexin-1 and galectin-1 in nasal polyps." (PMID 20549082, 2010). "Such variability raises questions about the possible involvement of galectin-1 in inflammation in nasal polyps." (PMID 20549082, 2010). "Another study evaluated the relation between galectin-1 and the administration of nasal budesonide in patients with nasal polyps;15 it showed that budesonide significantly raised galectin-1 expression in the polyps of allergic patients." (PMID 20549082, 2010). "Indeed, they showed that the expression of galectin-1 was significantly higher in nasal polyps than in middle turbinates." (PMID 24859692, 2014). "Using non-cross-reactive antibodies against galectin-1, -3, -4, -7, -8 and -9, we characterized the galectin profiles in chronic rhinosinusitis, nasal polyposis, inverted papillomas and squamous cell carcinomas." (PMID 24859692, 2014).
osteosarcoma (3 papers, 2018 to 2021). A usually aggressive malignant bone-forming mesenchymal neoplasm, predominantly affecting adolescents and young adults. "More recently, a novel interaction was identified between FGFR1 and galectin-1 (LGALS1)/galectin-3 (LGALS3) in osteosarcoma cells ectopically expressing FGFR1." (PMID 34068954, 2021). "Previous studies indicated that hypoxia promoted osteosarcoma development through increasing immunomodulatory proteins such as macrophage migration inhibitory factor (MIF), Galectin-1, and so on." (PMID 33816483, 2021).
Pleural effusion (3 papers, 2020 to 2021). The presence of an excessive amount of fluid in the pleural cavity. "Pleural effusion Galectin-1, NRG1-β1, Osteopontin, Mesothelin, shed SDC-1, VEGF and TIMP-1 levels are more reliable diagnostic biomarkers than HGF and MMP in pleural effusion." (PMID 32731396, 2020).
proliferative diabetic retinopathy (3 papers, 2017 to 2023). Advanced retinopathy due to diabetes mellitus characterized by the formation of new vessels in the retina. "Supporting the clinical relevance of these findings, we found increased levels of galectin-1 in aqueous humor from patients with proliferative diabetic retinopathy and neovascular glaucoma." (PMID 28455954, 2017).
acute kidney injury (2 papers, 2021 to 2023). Sudden and sustained deterioration of the kidney function characterized by decreased glomerular filtration rate, increased serum creatinine or oliguria. "Multivariate associations of the galectin-1 tertiles and factors with acute kidney injury within 48 h after intensive care unit admission (forward stepwise multivariate regression model)." (PMID 34559847, 2021). "Recent research showed that induction of kidney fibrogenesis through the accumulation of LGALS1 and cell matrix proteins by modulating protein synthesis in the kidney cortex of diabetic mice might play a major role in the pathological changes seen in DN, leading to renal failure." (PMID 38115247, 2023).